STAT3 (signal transducer and activator of transcription 3)
Diseases named in the same sentence as STAT3 in open-access papers (continued):
Sharing a sentence is not in itself a finding about the gene and the disease.
tumor (continued). "In tumour samples from patients with melanoma and prostate cancer, the mechanism involves the activation of intrinsic STAT3 in B cells leading to the secretion of angiogenic factors S1PR1, MMP9, HIF1a, VEGF, and their accumulation around micro vessels in the tumour." (PMID 35350071, 2022). "This review focuses on the crucial roles of two important transcription regulators (i.e., STAT3 and NRF2) and their interactions in the tumor microenvironment to identify potential antitumor drug targets and ultimately improve the health and survival of cancer patients." (PMID 36557902, 2022). "We further showed that knockdown of PVT1 suppressed tumor cell proliferation and metastasis in vitro and in vivo, while ectopic expression of PVT1 increased tumor growth and migration, which were rescued by silencing of either CypB or STAT3." (PMID 36266267, 2022). "Moreover, tumour immunity, such as the inflammatory response, IL6/JAK/STAT3 signalling and IL2/STAT5 signalling, was prominently enriched in parental HCC cells." (PMID 36275751, 2022). "In vivo tumor xenograft experiments showed that knockdown of circZFR inhibited tumor growth and weakened DDP resistance, while CAFs-derived exosomes increased circZFR level, inhibited the STAT3/NF-κB pathway, promoted tumor growth and enhanced DDP resistance." (PMID 35139763, 2022). "CD44 has been tightly linked to EMT, as it is upregulated by TGFβ, is directly involved with STAT3, β-catenin, and AKT signaling, and promotes tumor invasion and metastasis by contributing to the adhesion of cancer cells to the endothelium and fibronectin-enriched matrices." (PMID 36358747, 2022). "Targeting of the STAT3 pathway is a crucial point, as activation leads to increased production of vascular endothelial growth factor (VEGF), an angiogenic factor important for tumour development, invasion, and metastasis." (PMID 36084109, 2022). "Third, correlative studies of biomarkers driven by STAT3 activity, signaling pathway abnormalities, and/or immunotherapy (e.g., PD-1/ PD-L1 expression on the tumor or tumor-infiltrating cells) were not performed." (PMID 35267638, 2022). "STAT3 is known to activate matrix metalloproteinase 2/9 (MMP2/9) gene expression, which could mediate an enhancement effect on tumor invasiveness." (PMID 35463323, 2022). "Furthermore, diacerin inhibits IL-6-induced STAT3 nuclear localization and transcriptional activity in TNBC cells, and significantly reduces tumor volume and induces apoptosis when compared to vehicle treated mice." (PMID 35371975, 2022). "In conclusion, the findings from our studies suggest that the tyrosine kinase inhibitor sorafenib exhibits anti-tumor activity on its own through the inhibition of proliferation and the induction of apoptosis via inhibition of the ERK/MAPK and STAT3 pathways in OSA cells." (PMID 36012610, 2022). "So, the inflammatory environment in tumor tissues could be mediated by EGFR via NF-κΒ and STAT3, and the blocking of EGFR signaling can suppress the promotion of tumor inflammations." (PMID 36438839, 2022). "The potential role of apigenin was investigated previously; it prevents the growth and development of tumor cells by inhibiting JAK/SRC phosphorylation, resulting in the suppression of STAT3 activation, which further inhibits the transference of STAT dimers to the nucleus." (PMID 35807549, 2022).
tumor (continued). "Our study showed that DCZ0415 inactivates STAT3, which could be a reversing primary function of STAT3, leading to anticancer immunity and reduced MC38 tumours." (PMID 35194944, 2022). "It is suggested that decreased SOCS1 expression may induce signal transducer and activator of transcription 3 (STAT3) phosphorylation, ultimately resulting in unrestricted tumor cell growth." (PMID 36143213, 2022). "In our study, the expression of STAT3 and/or phospho-STAT3 (Tyr705) in FISSs did not correlate with tumor grading." (PMID 35836213, 2022). "For example, it has been reported that inhibition of the IL-6-JAK/STAT-3 signaling pathway in CRPC cells (C4-2 and CWR22Rv1) sensitizes tumor cells to NK cell-mediated cytotoxic action through changes in the PDL-1 ligand interaction and the expression of NKG2D." (PMID 35465350, 2022). "MDSCs mainly inhibit T cell function by producing arginase I (Arg1), reactive oxygen species (ROS), and immunosuppressive cytokines such as IL-10 and TGFβ through activating STAT3, C/EBPβ, PI3K, and MAPK signaling pathways, which skews MDSCs into M2-like tumor-promoting phenotype." (PMID 35785030, 2022). "Furthermore, STAT3 binds to both Mcl-1, Bcl-2, VEGF, and Survivin promoters, preventing CRC cell apoptosis and promoting tumor angiogenesis." (PMID 35884974, 2022). "Indeed, phosphorylation of STAT3-induced marked increases in HCC generation, tumor number, and tumor size in mice." (PMID 36380016, 2022). "Additionally, cytokines and growth factors in the TME, particularly IL-6, EGF, and hepatocyte growth factor, suppress anoikis by activating tumor cell signaling pathways, including the RAS-MAPK, PI3K-mechanistic target of rapamycin kinase, and STAT3 pathways." (PMID 36010693, 2022). "Src, a cell membrane-associated non-receptor tyrosine kinase is known to activate STAT3 pathway and plays a decisive role in cell proliferation differentiation and migration of tumor cells." (PMID 35401182, 2022). "Verifying findings from our in vitro assays, ruxolitinib but not propranolol suppressed RM9 tumor-induced STAT3 phosphorylation in white adipose tissue." (PMID 35785158, 2022). "CAF-assisted contractility of this tumor matrix induces signaling pathways (e.g., NF-kB, JAK/STAT3), in conjunction with the direct interaction of plasminogen activator inhibitor-1 (PAI-1) with respective cell surface receptors (LRP1, uPAR) on inflammatory and cancer cells." (PMID 36361831, 2022). "CCL5/CCR5 signaling mediates signal transduction cascades related to tumor progression, including PI3K/Akt, JAK/STAT3, MAPK/ERK, and NF-kB, involving in tumor growth, metastasis, cancer stem cell expansion, DNA damage repair, and angiogenesis and metabolic reprograming." (PMID 35784750, 2022). "Type II IL-4 receptor signaling may activate STAT3/6, PI3K/Akt, and ERK1/2 signaling pathways and contribute to tumor progression, and this is the first study linking type II IL-4 receptor signaling with HCC progression." (PMID 35721518, 2022). "Since STAT3, ERK1/2, and WNT/β-catenin are key oncogenic signaling pathways in CRC, we examined phosphorylation of STAT3 and ERK1/2 as well as nuclear localization of β-catenin in the tumor cell compartment of Phd2+/– and WT control tumors by IHC." (PMID 36509284, 2022). "This sex disparity is characterized by increased NF-κB signaling in males lacking epithelial STAT3, which drives tumor-promoting inflammation." (PMID 35406557, 2022). "Under hypoxic conditions, the dominant negative mutant (DN)-STAT3 is highly expressed, thereby exerting a negative effect on tumor growth and angiogenesis." (PMID 36362294, 2022). "It is tempting to speculate that STAT3- and PROM1-driven autophagy signaling pathways play key roles in modulating GBM plasticity and heterogeneity, thereby facilitating GBM tumor progression." (PMID 40396025, 2022).
tumor (continued). "Activation of STAT3 by IL-6 allows expression of cell cycle-promoting proteins such as cyclin D1, D2, and c-MYC and downregulation of cyclin-dependent kinase inhibitor p21, facilitating entry into the cell cycle, thus enhancing the growth of the tumour." (PMID 36429126, 2022). "In line with our results, STAT3 promotes GSC maintenance, tumor invasion, or immune evasion in GB." (PMID 35562901, 2022). "AKR1C1 is also a key component for the phosphorylation of STAT3 and it could facilitate the interaction of STAT3 with its upstream kinase JAK2, which promotes tumor metastasis in NSCLC." (PMID 35370661, 2022). "STAT3 and HIF-1α are known to interfere with tumor suppression and increase tumor angiogenesis." (PMID 35482149, 2022). "Stromal CM induced activation of JNK and STAT3 pathways in the tumour cells in the presence and absence of SULF2, with JNK inhibition suppressing both SULF2-dependent and independent Hep3B spheroids growth." (PMID 36589727, 2022). "In mouse mammary fat pad xenografts, ENSA knockdown resulted in a significant reduction in the tumor growth of MDA-MB-231 cells, which could be completely rescued by overexpression of ENSA and mostly rescued by overexpression of STAT3." (PMID 35145111, 2022). "Tumor is one of the important factors affecting human life and health in today’s world, and scientists have studied it extensively and deeply, among which autophagy and JAK/STAT3 signaling pathway are two important research directions." (PMID 35559037, 2022). "STAT3 knockdown abolished osteoclast- or IL-19–induced STAT3 phosphorylation in tumor cells, but did not affect upstream JAK1 phosphorylation." (PMID 36006737, 2022). "STAT3 inhibition showed a minor, but not significant impact in tumor progression despite being implanted in Rag2/IL2rg-/- mice." (PMID 36443756, 2022). "Both Stat3fl/fl Mx1-Cre and Stat3fl/fl Ncr1-iCre mice demonstrated that lack of STAT3 enhances NK cell-mediated surveillance in different transplantable tumor models." (PMID 35865518, 2022). "Although the activation of the IL-6/STAT3 signal has been primarily identified as being necessary for the proliferation of several types of CSCs, tumor-derived erythropoietin, mainly released under hypoxic conditions, also activates the JAK2–STAT3 axis in breast CSCs and promotes self-renewal." (PMID 36010693, 2022). "Moreover, combined blockade of STAT3/5 activity with a selective SH2 domain inhibitor, AC-4-130, effectively obstructs tumor development in vivo." (PMID 36045346, 2022). "The oncogenic transcription factor STAT3 acts as a signaling hub molecule involved in regulation of most, if not all hallmarks of cancer, including proliferation, tumor invasion, altered cellular metabolism, angiogenesis, immune evasion and cell survival." (PMID 35053502, 2022). "Taken together, STAT1 and STAT3 signaling pathways are tightly interconnected and IFN-γ/STAT1 target genes may be activated in a proinflammatory IL-6-containing tumor microenvironment." (PMID 35267462, 2022). "Bioinformatic analysis and mechanistic assessment reveals IGFBP2 upregulated indoleamine 2, 3-dioxygenase (IDO) by activating signal transducer and activator of transcription 3 (STAT3) signaling in PDAC cells, thus inducing Treg differentiation and an immunosuppressive tumor microenvironment." (PMID 36556226, 2022). "Additionally, S1P–S1PR1 signaling activates STAT3 by upregulating IL-6 and JAK2 activity to promote tumor growth and metastasis." (PMID 35565311, 2022). "The result of immunohistochemical detection shows that the expression of STAT3 was significantly correlated with pTNM stage (P < 0.05), but not with gender, age, tumor differentiation, pT, and pN." (PMID 36225196, 2022). "In addition, TGF-β, JAK/STAT, and IL-6/STAT3 signaling pathways contributed prominently to the stemness regulation of CD44+ cells, resulting in their vital roles in tumor initiation and growth." (PMID 36293184, 2022).
tumor (continued). "In particular, in PCa pSTAT-3 and IL-6R are present in 95% of metastatic niches of patients who die of castration-resistant PCa (CRPC); this suggests that in PCa, the activation of STAT-3 mediated by IL-6, IL-10 and EGF serves an important role for tumor progression and development of metastasis." (PMID 35703345, 2022). "In addition to EGFR, IL-6 signaling also activates STAT3, and IL6R blockade significantly inhibits tumor progression." (PMID 36010693, 2022). "Oxidative stress is involved in tumor development, and in HepG2 cells, it has been shown that exposure to H2O2 decreases PIAS3 expression while increasing STAT3 expression and that overexpression of PIAS3 recovers the anti-oxidative response, decreases cell migration and invasion capacity." (PMID 35887358, 2022). "TAM-derived IL-6 drives the crosstalk between MSCs associated with colorectal cancer, enhancing the migration properties of macrophages in TIME, and promoting tumor growth and metastasis through the IL-6/JAK2/STAT3 axis, subsequently activating the Pi3K/AKT/mTOR signaling." (PMID 35884974, 2022). "However, STAT3 and STAT5 have been studied more thoroughly, while the role of STAT1, STAT2, STAT4, and STAT6 in tumor development has been studied less thoroughly." (PMID 35244291, 2022). "Moreover, STAT3 can regulate the expression of VEGF, a growth factor necessary for angiogenesis and tumor vasculature maintenance." (PMID 36080130, 2022). "As a result, pharmacological inhibition of Src would increase Cad11/gp130/Stat3 levels in tumors with high Src activity, hence increase, rather than decrease, the metastatic ability of the tumor, leading to a deterioration in clinical outcome." (PMID 35411090, 2022). "STAT3 is highly expressed and constitutively activated in TNBC cells, regulating the expression of their downstream target genes, promoting proliferation and tumor aggressiveness." (PMID 35626741, 2022). "In TME, IL-6 could drive tumor cells proliferation, invasiveness, and metastasis through activating JAK/STAT3 signaling pathway which could in return promote IL-6 transcription." (PMID 36685973, 2022). "It was also reported that activation of STAT3 could promote the expression of MMP2 and MMP9 in tumor cells, thus upregulate their ability of invasion and metastasis." (PMID 36188592, 2022). "In vivo study, there’s no significantly change in tumor volume after Stat3 knockdown compared with shNC-Control group, but the tumor size decreased in the group of sorafenib plus shStat3 group compared with shStat3 group." (PMID 35252007, 2022). "Oral or intra-peritoneal delivery of H120 or H182 as a single agent inhibited human TNBC xenografts growth, and H278 (H182 hydrochloric acid salt) combined with radiation therapy completely blocked tumor growth and prolonged survival in mouse TNBC syngeneic models that harboraberrantly-active Stat3." (PMID 35276290, 2022). "These cells are not transformed so that, unlike tumor cells, the relationship between Src, cadherin-11, and Stat3 can be examined in the absence of confounding pathways." (PMID 35411090, 2022). "In this experiment, ABP treatment inhibited the phosphorylation of STAT3, reduced the expression of IL-6 and increased the expression of IL-10, indicating that the anti-inflammatory effect of ABP may be one of its anti-tumor effects." (PMID 35264966, 2022). "GYP significantly reduced the expression of STAT3, EGFR, TYMS and MAPK14 in tumor tissues, while cisplatin combined with GYP could further reduce the expression of STAT3, TYMS and MAPK14 in tumor tissues." (PMID 36532716, 2022). "In stage I and II of COAD, IL6/STAT3 signaling pathway, TGF-β signaling and FC receptor response have strong activity, which revealed the inflammatory activation of the immune response in the early stage of the tumor." (PMID 35992347, 2022).
tumor (continued). "Phospho-STAT3 (Tyr705) expression is closely correlated with the histological grading and intratumor microvessel density in HCC.Additionally, STAT3 activation is correlated with a better or worse prognosis depending on the tumor type." (PMID 35836213, 2022). "In addition, Ganetespib and 17-AAG decreased PD-L1 transcription through destabilizing Hsp90 clients MYC and STAT3 in monocytes and tumor cells at the sub-cytotoxic concentration, and Ganetespib diminished PD-L1 level on MC38 tumor cells in vivo." (PMID 36341371, 2022). "This is a tumour suppressor gene that targets essential pathways involved in tumorigeneses such as Janus protein tyrosine kinase (JAK), c-Myc and signal traducer and activator of transcription 3 (STAT3)." (PMID 36295655, 2022). "Therefore, IL-6 enhances tumor cell proliferation, migration, and invasion via the JAK2/STAT3 signaling pathway." (PMID 36313702, 2022). "Moreover, the inflammatory IL-6/STAT3 regulatory circuit, which is maintained by pancreatic stromal cells in the TME, modulates tumor aggressiveness and metastatic properties." (PMID 35993361, 2022). "The miR-21a in exosomes from Lewis lung carcinoma cells accelerates tumor growth through targeting programmed cell death protein 4 (PDCD4) through activating the autocrine production of IL-6 and phosphorylation of the STAT3 signaling pathway and thus enhances the expansion of MDSCs and tumor growth." (PMID 35634311, 2022). "In addition, the protein levels of STAT3 and p‐STAT3 in tumor tissues were significantly decreased and thus potently reduced M2‐like TAMs, as well as, LLC tumor progression." (PMID 37323705, 2022). "Previous studies demonstrated that STAT3 can directly or indirectly interact with the promoters of cyclin D1, Twist, MMP2, MMP7, MMP9, VEGF, upregulate their expression and regulate cell proliferation, tumor metastasis and angiogenesis." (PMID 36295083, 2022). "Gender, age, pT, pTNM stage, tumor location, STAT3 expression, radiotherapy, and chemotherapy were not related to the 5-year survival rate." (PMID 36225196, 2022). "To determine whether DIM mediated inhibitory effect on MDSCs via targeting miR-21/STAT3 signaling pathway, we also evaluated the therapeutic effects of DIM in miR-21−/− mice bearing 4T1 tumor." (PMID 35773674, 2022). "In the tumor microenvironment, STAT3 regulates NF-κB signaling in tumor and non-transformed stromal cells." (PMID 36061200, 2022). "Importantly, key oncogenic signalling pathways, including ERK1/2, mTOR, p38, MSK, STAT5, STAT3 and PDGF, were induced in CAFs and less so in the mesothelial cells from the same tumour." (PMID 36293328, 2022). "STAT3 bound the VEGF promoter and transactivated VEGF to touch upon tumor angiogenesis." (PMID 35784750, 2022). "Moreover, IL-6 in the tumor microenvironment promotes tumor progression resistance to chemo- and radiotherapy through the JAK/STAT3 signaling pathway." (PMID 36362245, 2022). "The STAT3 inhibitor SOCS3 was significantly suppressed during tumour development as compared with tissue with mucosal inflammation lacking tumours." (PMID 35793807, 2022). "Various genes are regulated by STAT3 including MMPs, TWIST1 and VEGF, and studies have suggested that these genes trigger metastasis, cell migration and tumor formation, but the expression of these genes is inhibited by apigenin treatment, which significantly blocked the activity of STAT3." (PMID 35807549, 2022). "Consistent with the view that the ROBO3/AXL regulatory network promoted tumor aggressiveness through the IL-6/STAT3 axis, we observed significantly reduced expression of AXL and p-STAT3 in dCas9-ROBO3 tumors, whereas tumors derived from LacZ showed robust expression of AXL and p-STAT3." (PMID 35993361, 2022). "STAT3 plays a key role in the formation of ALCL by mimicking physiological pro-growth signals, such as the IL2 and TCR signaling pathways, promoting the proliferation and survival of tumor cells." (PMID 35406421, 2022).